RN7SL759P (RNA, 7SL, cytoplasmic 759, pseudogene)
Gene: Miscellaneous RNA gene on chromosome 15 (20,570,886 to 20,571,175, forward strand). Ensembl gene ENSG00000278497.
Homologues: Orthologues: pig Metazoa_SRP (54% identical), macaque Metazoa_SRP (48% identical). Paralogues in human: RN7SL545P (100% identical), RN7SL536P (99% identical), Metazoa_SRP (99% identical), RN7SL106P (99% identical), RN7SL238P (99% identical), RN7SL196P (88% identical), RN7SL286P (88% identical), RN7SL539P (88% identical), RN7SL796P (88% identical), RN7SL214P (79% identical), RN7SL736P (79% identical), RN7SL209P (78% identical), and 702 more.